LEP (leptin)
Diseases named in the same sentence as LEP in open-access papers (continued):
Sharing a sentence is not in itself a finding about the gene and the disease.
Obesity (continued). "Using the high fat diet (HFD)-induced obese mouse model, we found that basal plasma norepinephrine, the principal catecholamine as an index of SNS activity, was persistently elevated and highly correlated with plasma leptin concentration during obesity development." (PMID 31682617, 2019). "These approaches regenerate the hope of using leptin as an effective treatment for obesity." (PMID 31717265, 2019). "Our study introduced adiponectin and leptin as indicator of MetS and obesity respectively." (PMID 31341853, 2019). "In obesity, leptin central effects (i.e., induction of energy expenditure) is impaired, therefore its local effects may prevail and contribute to white adipose tissue expansion and enhanced inflammatory milieu." (PMID 31920961, 2019). "The proadipogenic role of leptin unraveled here may be of especial relevance during obesity, when its central signaling is defective." (PMID 31920961, 2019). "Leptin signaling, which modulates satiety, exhibits circadian variation and may link clock gene fluctuations with metabolic diseases such as diabetes and obesity." (PMID 31671606, 2019). "Leptin plays an important role in obesity-induced oxidative stress." (PMID 31456748, 2019). "Hence, our findings offer suggestions for future investigation of this phenomenon and contribute to the understanding of the role of insulin and leptin resistance in obesity pathogenesis in humans." (PMID 30886629, 2019). "Fourth, additional hormonal assessment including sex steroids, IGF-1 and hormones modulating satiety such as leptin and ghrelin, may further explain the differences in obesity rates with abnormal sleep habits." (PMID 30971731, 2019). "Thus, direct delivery of leptin into the CNS likely circumvents potential leptin transporter defects that gradually develop in obesity." (PMID 31222048, 2019). "Like insulin, leptin’s signaling capacity in the brain is reduced in conjunction with obesity." (PMID 30814963, 2019). "Because of the pivotal role hypothalamic ER stress plays in leptin resistance and obesity development, a screen was performed to identify small molecules which might promote weight loss through its amelioration." (PMID 31225498, 2019). "Thus, it does appear that both leptin and blood pressure contribute to cardiac hypertrophy with obesity in mice and humans." (PMID 31842996, 2019). "In addition to the deleterious effect of leptin resistance, we have recently elucidated another mechanism which drives defective NK cells in human obesity." (PMID 31018563, 2019). "A meta-analysis has revealed that the genes of pharmacodynamic targets of antipsychotics like HTR2C, DRD2, ADRA2A and genes implicated in obesity such as MC4R, GNB3, FTO, LEP, LEPR, BDNF, and INSIG2 seem to be consistently relevant to antipsychotic-induced weight gain." (PMID 32116676, 2019). "Hence, defects in hepatic leptin action, which occur in the state of diet-induced obesity, impair the function of the liver, leading to fat accumulation." (PMID 31842467, 2019). "Leptin, an adipokine, is strongly concentrated in people with obesity." (PMID 31684107, 2019). "In turn, leptin is also positively correlated with obesity and irisin itself." (PMID 31065382, 2019). "Finally, we will summarize new data regarding the obesity paradox based on the beneficial effect of overweight on the results of immunotherapy of cancer and discuss the possible role of leptin." (PMID 31380268, 2019). "Furthermore, the subgroup with the greatest risk of developing arterial hypertension was the one presenting both obesity and a high leptin/adiponectin ratio." (PMID 31262082, 2019). "Therefore, it can be concluded that higher serum leptin concentration and FLI, as well as lower serum sOBR and kisspeptin concentrations, are significantly associated with obesity in postmenopausal women." (PMID 31871451, 2019).
Obesity (continued). "It appears that the BMI above normal level influences the relationship between serum leptin and menstrual cycle, and obesity induces abnormal rhythmicity that has been hypothesized to contribute to leptin resistance in obesity." (PMID 32025443, 2019). "However, do the higher leptin levels in obesity suppress appetite and increase energy expenditure to a greater extent than do merely “sufficient” leptin levels?" (PMID 30357355, 2019). "These salivary biomarkers correspond well to the established circulating plasma biomarkers associated with obesity, reflecting the metabolic aspect (e.g., insulin and leptin) as well as the inflammatory aspect (e.g., CRP and adiponectin) of the mechanism underlying obesity." (PMID 31236292, 2019). "To determine whether AHR treatment could ameliorate obesity-related abnormalities in blood parameters, we analyzed circulating total cholesterol, triglyceride, leptin, and adiponectin levels." (PMID 31547031, 2019). "Although no previous works link this gene with plasma leptin concentrations, there are prior known associations with obesity and diabetes." (PMID 31766143, 2019). "This led us to ask whether basal plasma norepinephrine, the principal catecholamine as an index of sympathetic activity, elevates and correlates with plasma leptin in obesity." (PMID 31682617, 2019). "Likewise, data from a genetic study further demonstrated that blocking hypothalamic NF-κB signaling reverses hypothalamic leptin resistance and promotes weight loss and reduced food intake in HFD-induced obesity." (PMID 31731503, 2019). "Therefore, the improvement of leptin resistance by regulating the JAK2-STAT3 signaling pathway effectively exerts anti-obesity activity." (PMID 29874843, 2018). "Patients with obesity have higher levels of leptin and display leptin resistance." (PMID 30151379, 2018). "Hence, there is a great scope for active research to identify a specific pharmacotherapy candidate to improve leptin signaling in obesity." (PMID 29868503, 2018). "Early warning signatures of adverse nutritional imprinting could be anticipated from leptin and adiponectin expression in adipose tissue, long before the onset of obesity." (PMID 29329236, 2018). "In summary, results highlight relationships of leptin and hsCRP with obesity and type 2 diabetes." (PMID 29422086, 2018). "We previously showed that SELENOM knockout mice develop obesity and decreased leptin signaling." (PMID 29385050, 2018). "Besides leptin, other obesity-related metabolites, like adiponectin or IL-6, are shown to influence NK cell functionality." (PMID 29560551, 2018). "Further research, however, has shown that leptin transport can be reduced in obesity." (PMID 30618559, 2018). "However, previous studies have reported that blood plasma concentrations of leptin are 11.6 ng/ml in healthy individuals and 34.7 ng/ml in patients with obesity." (PMID 30269202, 2018). "Stellate cells in the liver also appear to retain their responsiveness to leptin in obesity; the hormone stimulates those cells to synthesize collagen and may thereby contribute to hepatic fibrosis and cirrhosis." (PMID 29632515, 2018). "Although leptin levels increase in obesity, insensitivity prevents it from fulfilling its function." (PMID 30618559, 2018). "On the basis of the role of leptin, striped hamsters may be becoming an animal model showing resistance to overweight or obesity." (PMID 29343842, 2018). "In addition, rats selectively bred to develop diet-induced obesity were functionally leptin resistant at age 4 weeks, despite normal leptin transport across the BBB." (PMID 29748097, 2018). "A more debated hypothesis positions the physiological components of obesity, including glucose, insulin, and leptin signaling as key contributors to the etiology of OSA." (PMID 30127766, 2018).
Obesity (continued). "This review will concentrate on the original obesity gene, leptin (LEP) and its receptor (LEPR), together with a gene that has been identified as having variants of strong effect giving rise to both monogenic obesity and obesity in the general population, the melanocortin-4 receptor (MC4R)." (PMID 30121879, 2018). "In men leptin was 1.88 ± 0.76 ng/mL in those with low BMI, 5.09 ± 4.57 ng/mL in those with normal BMI, 9.70 ± 4.14 ng/mL in those where the BMI indicated being overweight, and 20.41 ± 14.99 ng/mL in those where the BMI indicated obesity." (PMID 29890036, 2018). "Thus, finding a way to block or reverse the processes that mediate hypothalamic leptin signal attenuation is an attractive therapeutic strategy to reduce obesity and improve metabolic homeostasis." (PMID 29311632, 2018). "Serum leptin levels are increased in patients with obesity and insulin resistance." (PMID 29979770, 2018). "Likewise, a strong positive correlation between leptin concentrations and fat mass has been observed in children with obesity." (PMID 30285789, 2018). "Further mechanistic studies focused on the leptin pathway could have potential therapeutic action in common obesity-related complications of psoriasis." (PMID 29910742, 2018). "Targeting SOCS-3 expression and PTPs activity using appropriate inhibitors and implying ER stress reducing measures could help in reversing leptin insensitivity in obesity." (PMID 29868503, 2018). "In this context, any alteration in the mitochondrial performance induced by leptin will deeply affect heart functionality and may provide clues to explain the well-described relationship between obesity and cardiovascular diseases." (PMID 30154842, 2018). "We suggest that leptin signaling in perivascular cells may play a role in the integrity of the intracranial perivascular space and, consequently, provide a link between obesity and numerous brain diseases." (PMID 29410615, 2018). "We conclude that high levels of leptin and oxidative stress in testicular tissue may provide some evidence to clarify the mechanisms of male SH in obesity and DEHP." (PMID 29887939, 2018). "When leptin central signalling is disrupted by genetic modifications, NPY expression increases and POMC expression decreases, putting the organism into an anabolic state, and increasing the risk of obesity." (PMID 30241328, 2018). "It has been hypothesized that neuronal cell damage may occur in obesity due to changes in levels of hormones such as leptin and adipokines, and due to oxidative stress." (PMID 28739552, 2018). "However, several studies have demonstrated that leptin is correlated with obesity and asthma in both adults and children." (PMID 30050954, 2018). "There is a relationship between low-grade inflammatory state and leptin in obesity, suggesting that leptin could exert peripheral biological effects as a function of its cytokine-like structure." (PMID 29189992, 2018). "It was postulated that either estrogen induces changes in a number of synapses on POMC neurons, since sex differences were detected in the previous study as well; or that leptin is involved in synapse remodeling, since leptin is elevated in obesity and targets POMC neurons." (PMID 30254630, 2018). "Particularly, indices related to obesity (body weight, BMI, WHR, and fat percent), T2D (HbA1c and glycemic indices), hormones (testosterone, leptin), and T2D-related co-morbidities (obesity, hypertension, hyperlipidemia, and any psychiatric disorders, and PTSD) were different among the groups." (PMID 29596446, 2018). "Therefore, the improvement of leptin resistance by regulating the JAK2-STAT3 signaling pathway is the mechanism by which COSCs exerts effective anti-obesity activity in HFD-induced obese rats." (PMID 29874843, 2018).
Obesity (continued). "OSA can lead to activation of the sympathetic nervous system, increased leptin and ghrelin levels contributing to increased appetite and food intake, decreased adiponectin level, oxidative stress, inflammation and obesity which all ultimately contribute to insulin resistance." (PMID 30042730, 2018). "The studies selected showed, in addition to higher adipokine values among childrenand adolescents with obesity and diabetes, an association between WHR, skin folds,waist and hip circumference, percentage of body fat, body fat mass, US-CRP, leptin,vaspin, and white blood cell count." (PMID 29412431, 2018). "There are very few studies though addressing leptin-inflammatory effects in vivo, and the effects of leptin are confounded with the effects of other immunometabolism-modulating factors that are altered in diseases such as infection or obesity." (PMID 29467755, 2018). "Leptin increases with decreased renal function and is related to obesity and insulin resistance." (PMID 30228288, 2018). "While first known adipocyte hormone leptin suppresses appetite and genetic absence of which causes massive obesity, other hormones like adiponectin have just the opposite effect." (PMID 29480368, 2018). "Differential mRNA levels for leptin, IP-10 and IL-1β with 12- and 28-weeks of diet-induced obesity." (PMID 29527173, 2018). "Leptin- (ob/ob) or LEPR-deficient (db/db) mice for instance are morbidly obese due to uncontrolled food intake, whereas animals deficient for IL-6 develop mature onset obesity." (PMID 30224299, 2018). "Indeed, enhanced relaxant response of mesenteric arteries and increased leptin-mediated NO production in the mesenteric artery PVAT have been demonstrated at the early phase of diet-induced obesity in C57BL/6J mice." (PMID 29681862, 2018). "Several different mechanisms have been hypothesized to impair leptin responsiveness in the ARC in obesity [reviewed in Ref." (PMID 29632515, 2018). "Although the role of LEP and LEPR gene polymorphisms and their involvement in various diseases have been investigated extensively throughout the world in different populations, the association of LEP and LEPR variants with obesity, BMI, and MetS is still controversial." (PMID 30583468, 2018). "Further understanding of leptin resistance mechanisms could enable new leptin targeted therapies for obesity and diabetes in specific subsets of patients." (PMID 29910742, 2018). "Obesity is a major risk factor for development of T2D, and lacking of leptin or the leptin receptor (LepRb/ObRb) will develop severe obesity and insulin resistance." (PMID 30115855, 2018). "Contradictory results have been published about the effect of RSV on these markers of leptin signaling in different tissues, indicating that the duration of the treatment and the grade of obesity achieved can directly influence the effect of RSV in these tissues." (PMID 30441779, 2018). "Resistance to leptin with consequent hyperleptinaemia are metabolic conditions observed in obesity." (PMID 29322840, 2018). "It is therefore possible that carnosine supplementation may be more effective in reducing leptin concentrations in the presence of greater obesity and higher leptin concentrations; however, further studies are needed to confirm this." (PMID 30205427, 2018). "The aim of the current study is to determine whether changes in adiponectin and leptin may be relevant to consider the pathophysiology of obesity‐related diseases that are rapidly increasing in Benin." (PMID 29890036, 2018). "The multivariable logistic regression adjusted for age, sex, obesity and tissue plasminogen activator (tPa) showed that lower adiponectin (odds ratio [OR], 0.42; 95% confidence interval [CI], 0.31–0.56) and higher leptin levels (OR, 1.49; 95% CI, 1.31–1.69) are independent predictors for PTS." (PMID 29720688, 2018). "In general, as leptin increases with fat mass, it acts as an anti-obesity hormone." (PMID 30127766, 2018).
Obesity (continued). "In females, leptin was 16.34 ± 15.52 ng/mL in those with low BMI, 19.19 ± 10.71 ng/mL in those with normal BMI, 35.25 ± 16.13 ng/mL in those where the BMI indicated being overweight, and 48.82 ± 17.45 ng/mL in those where the BMI indicated obesity." (PMID 29890036, 2018). "Genome scans and association studies have linked LEPR to measures of adiposity including energy expenditure in: a population with elevated obesity levels, fat mass, skinfold and fat-free mass; BMI trends in childhood; and leptin levels, body composition, insulin dysregulation and glucose metabolism." (PMID 30121879, 2018). "Following the same line of thought, and due to the strong hormonal component in obesity, hormonal pathways (such as leptin and insulin-related) still deserve further investigations to identify novel molecular targets within the obesity-related pathways of these hormones." (PMID 30463389, 2018). "High concentrations of leptin induced by obesity lead to immune cell activation." (PMID 30618559, 2018). "Chronically elevated leptin levels in obesity may result in decreased responsiveness of pancreatic β-cell receptors and lead to increased insulin secretion, contributing to the occurrence of insulin resistance." (PMID 29551973, 2018). "CTRP3, combined with leptin and other bioactive components, may be acting to prevent the maternal transfer of obesity, through reducing food intake, stimulating metabolism, or a yet to be determined mechanism." (PMID 29527418, 2018). "In addition, animal study showed that skinny and obese mice overexpressing leptin demonstrated elevation of blood pressure, suggesting that leptin plays a role in the pathogenesis of obesity-related hypertension." (PMID 29675134, 2018). "Although leptin resistance in rodents and humans is reversed by dietary modification, inducements to reduce calorie intake and increase exercise have not proved particularly successful in most populations where obesity levels are high." (PMID 29311632, 2018). "This experimental study revealed that the levels of hypothalamic leptin and insulin in the cerebral blood of the obesity rats were significantly lower than those in the cerebral blood of the normal rats, whereas the result of those levels in the peripheral blood was opposite." (PMID 29853949, 2018). "Leptin resistance (LR) commonly occurs in diet-induced obesity (DIO) in mammals." (PMID 30405527, 2018). "A recent study proposed that the saponins derived from fungal endophytes could be potential inhibitors of leptin and may repair its resistance in obesity, and may modulates immune response in favor of host against multiple diseases." (PMID 29868503, 2018). "Supporting this observation, leptin-deficient mice were not hypertensive, despite severe obesity, pointing out that hyperleptinemia, not obesity, is the blood pressure regulator factor." (PMID 30618812, 2018). "Both leptin and resistin are two of the important adipokines, which are elevated in obesity." (PMID 29568521, 2018). "Moreover, T cell-mediated STAT3 promoted insulin resistance and obesity while leptin (satiety hormone) signaling relied on downstream STAT3 signaling." (PMID 30369883, 2018). "Also, many forms of obesity are characterized by an increased level of circulating leptin at the same time as many obese individuals are in fact resistant to leptin." (PMID 29321614, 2018). "Our data suggest that pericytic leptin signaling plays a role in the integrity of the intracranial perivascular space and, consequently, may provide a link between obesity and numerous brain diseases." (PMID 29410615, 2018). "An anorexigenic hormone that may participate in the termination of appetitive ingestive behaviors is leptin, the product of the obesity gene (Ob) secreted primarily from adipocytes." (PMID 29343842, 2018).